IL13 (interleukin 13)
Diseases named in the same sentence as IL13 in open-access papers (continued):
Sharing a sentence is not in itself a finding about the gene and the disease.
infection (continued). "This is so because IL-13-1112 TT genotype increases transcription of the cytokines leading to elevation of IL-13 cytokine and the cytokine enhances resistance to infection by schistosome in humans." (PMID 34048465, 2021). "After infection with N. brasiliensis, WT mice had increased Il13 mRNA expression in the lung on D2pi that further increased by D6pi." (PMID 34127548, 2021). "Reactome analysis of differentially regulated genes from whole tissue RNA-Seq revealed a significant enrichment of genes involved in IL-4 and IL-13 signaling in the infected lung (FDR adjusted P value = 0.03) on day 5 after infection." (PMID 34185704, 2021). "Marked increase of IL-13 expression was observed in DENV-1 infected PBMCs compared to mock infection (P = 0.006, multiple time points comparison); IL-13 production was above the limit of detection at very late time points (i.e. > 48 h post infection)." (PMID 34215212, 2021). "IL-33, in the presence of IL-25, potentiates ILC2 populations to produce IL-13 to promote intestinal remodeling to facilitate infection resistance with helminths and parasites." (PMID 33431701, 2021). "As expected, CD4+ T cells robustly upregulated type 2 cytokines IL-4, IL-5 and IL-13 by day 7 post-infection." (PMID 34237106, 2021). "Infection with the nematode N. brasiliensis resulted in an increase in lung Relmα-dtTomato+ interstitial macrophages and eosinophils in an IL-4/IL-13- and STAT6-dependent manner." (PMID 34557875, 2021). "The effect of HRV16 infection on epithelial gene expression was in many ways similar to that observed during IL-13-induced MCM, which was confirmed by multivariate analysis." (PMID 34140575, 2021). "We observed few IL-13+ ILC2s within small intestinal PP in homeostasis, but at 5 days post-infection (dpi) with N. brasiliensis, soon after worm arrival in the gut, ILC2 numbers in PP significantly increased." (PMID 34484215, 2021). "In contrast, in the intestinal mucosa, we observed an increase in ILC2-T cell interactions post-infection, including some of prolonged duration, as well as increased IL-13+ ILC2 movement." (PMID 34484215, 2021). "RNA-Seq analysis was performed on whole lung tissue from IL-13–neutralized and control-treated mice at day 5 after infection to evaluate transcriptional responses downstream of IL-13." (PMID 34185704, 2021). "Naïve macrophages can be activated either classically into a proinflammatory M1 phenotype by IFNγ, TNF-α, and TLR ligands to defend against infection or into an anti-inflammatory M2 phenotype by IL-4 and IL-13 to aid in healing." (PMID 34539613, 2021). "On the other hand, IL-13 and GM-CSF levels were substantially elevated in the rAd5-LcrV monovalent vaccinated mice (prior to infection) as compared to animals that were immunized with the rAd5-YFV trivalent vaccine." (PMID 33514747, 2021). "In contrast, goblet cell metaplasia was subtly, albeit significantly, induced following infection, and this increase was reduced by neutralization of IL-13." (PMID 34185704, 2021). "For instance, in the mouse model of RSV infection, anti-TSLP antibodies administered either 6 or 36 hours after infection resulted in a significant decrease in IL-13-expressing ILC2." (PMID 32397226, 2020). "In the rat model of schistosomiasis, primary infection and secondary infection induce a Th2 cytokine response characterized by increased expression of IL-4, IL-5, and IL-13, which is driven by egg production in mice." (PMID 33013763, 2020). "Granuloma formation around schistosome eggs is dependent on T cell-derived IL-4/IL-13 secretion and AAMs are critical to prevent a fatal infection in mice." (PMID 33042153, 2020). "Further, Cse−/− mice had lower levels of anti-inflammatory cytokines IL-10 and IL-13 at 2 weeks post-infection, which was followed by a significant increase in IL-10 levels after 3 weeks of infection." (PMID 33330130, 2020).
infection (continued). "Subsequently, neutralization of IL-25 during the course of infection or use of IL-17RB deficient mice reduced airway mucus measured by PAS staining, and accumulation of IL-5 and IL-13 measured in re-stimulated draining lymph node cell supernatants." (PMID 32397226, 2020). "IL-25 is mainly produced by tuft cells in the gut epithelium upon infection with N. brasiliensis, leading to activation of Th2 cells and ILC2s, which will start producing IL-13 in response." (PMID 33042153, 2020). "Further, type 2 innate lymphoid cell (ILC2) responses are at their most prominent in early infection, and IL-4/IL-13 from this subset is likely to contribute to the Th2 skewing observed in our model." (PMID 33117327, 2020). "This increase of the Treg pathway was associated with a concomitant increase of Th2 cytokines (IL-5 and IL-13), as observed in several other models of infection and inflammatory diseases." (PMID 32571430, 2020). "After 4 weeks of infection, the host's immune response shifts to a Th2 type, producing cytokines such as IL-4, IL-10, and IL-13." (PMID 32373112, 2020). "It was suggested that low levels of TNF-α, IL-2, IL-4, and IL-13 during early infection were predictive markers of chronic joint pain." (PMID 32471152, 2020). "Lower levels of the antiinflammatory cytokines, IL-10 and IL-13, after 2 wk of infection, followed by a significant increase in IL-10 levels after 3 wk of infection in CSE−/− mice reflects controlling mechanisms of the proinflammatory response in CSE−/− mice." (PMID 32139610, 2020). "In contrast, early production of excessive IL-10 and IL-13 antiinflammatory cytokines observed in the serum of WT mouse after 2 wk of infection promoted Mtb growth." (PMID 32139610, 2020). "At 14 days post infection (directly after treatment) very high concentrations of IL-2, IL-13, IL-10, IFNγ, IL-6, and TNFα were observed." (PMID 32226027, 2020). "Similar reductions in AHR and levels of IL-5 and IL-13 in the BALF were seen after re-infection when anti-TSLP was administered prior to the primary infection of neonatal mice compared to mice administered a control antibody." (PMID 32397226, 2020). "It has been reported that interleukin (IL)-4, IFN-γ, TNF, IL-13, and IL-1 are involved in anti-infection effects." (PMID 33013763, 2020). "L. major lysate-stimulated lymphocytes from EBI3−/− mice secrete fewer IFN-γ and high IL-4, IL-10, and IL-13 as compared to the lymphocytes from the control mice on the second and third week post-infection." (PMID 32849534, 2020). "Anti-HMGB1 therapy significantly reduced the concentrations of IL-4, IL-5, and IL-13 in the BALF at day 21 post-infection compared to a group that was infected and treated with control antibodies." (PMID 32397226, 2020). "By contrast and as expected, an increase in Il13 mRNA occurred at 2 weeks post infection, a time point at which adult worms have left the mucosa and have colonized the intestinal lumen." (PMID 31776431, 2020). "Animals treated with mα-IL-25 showed a similar cytokine profile to non-treated mice, and in both groups, a type-2 response was generated with elevated gene expression of IL-4 and IL-13 after the challenge infection." (PMID 33276813, 2020). "Secondary infection at 10 wppt was characterized by the significant upregulation of IL-4 and IL-13 and unaltered or downregulation of type-1 cytokines, such as, IL-12p35/IL-12p40 or IFN-γ." (PMID 33276813, 2020). "Previous work has suggested that the IL-13 controlled epithelial escalator was most successful at expelling worms at approximately day 14 post infection when smaller larval stages reside in the lower/mid region of the crypt where epithelial cells move faster." (PMID 31730667, 2019). "IL-17A stimulation resulted in marked down-regulation of IL-13 at all-time points post-infection when compared to untreated controls." (PMID 31681209, 2019).
infection (continued). "The role of intestinal ILC2 during pathogen infection is to promote intestinal epithelium integrity via IL-5, IL-13, and amphiregulin, which leads goblet hyperplasia and mucus production." (PMID 30770814, 2019). "Under natural conditions, infection occurs by repeated low-level ingestion of eggs; IL-13-dependent protective immunity is slow to develop and partial at best." (PMID 31138806, 2019). "For instance, a study of influenza A virus shows that transcriptionally active remnants of the virus can remain in lung cells once infection has cleared and can also contribute to chronic lung disease partially accounted for by IL-13 expression." (PMID 30759882, 2019). "Resistance to these infections is dependent on the generation of a robust type 2 cytokine response, in particular production of IL-13." (PMID 31582416, 2019). "Two cell populations determine leishmanial condition: Th1 (IFN-γ, IL-2) in the protective condition and Th2 (IL-4, IL-10, and IL-13) in progressive infection." (PMID 30834079, 2019). "We reasoned that infection mediated by TIM-4 obscured the subtler effects of IL-4/IL-13 treatment and the effect of IL-4/IL-13 would likely be more profound in TIM-4-null pmacs." (PMID 31825972, 2019). "Corresponding to this finding, infection with high-uptake C. neoformans resulted in enhanced arginase enzyme activity, elevated IL-4 and IL-13 and lowered IL-17 in the bronchoalveolar lavage." (PMID 30520685, 2019). "To examine the involvement of c-Maf, Bach-1, and Elmo-1 in Mtb-growth promotion within M(IL-4/IL-13) BMDMs, we knocked-down these target genes using GapmeRs in M(IL-4/IL-13) BMDMs prior to infection with Mtb." (PMID 30941122, 2019). "Here we show that IL-4/IL-13 polarization of murine peritoneal macrophages enhances EBOV GP-dependent infection by increasing cell surface expression of CLRs." (PMID 31825972, 2019). "The present review section is based on a PubMed search using the strategy: (IL-13/ IL-13R/ Interleukin-13/ Interleukin-13 receptor AND ‘infection’) in: abstract/title; cut-off 10 October 2018." (PMID 30759882, 2019). "The same was observed for the IL-13 expression in the spleen indicating a delayed systemic response to infection." (PMID 30915083, 2019). "In contrast, experimental studies using gene-deficient mice in L. donovani infections have indicated that the control of not only primary infection, but also successful chemotherapy and successful vaccination is IL-4, IL-13, and IL-4Rα signaling-dependent." (PMID 31475014, 2019). "Intriguingly the mRNA levels of RELM-β in exfoliated cells reflected the local GATA-3 and IL-13 expression in mLN during infection." (PMID 30915083, 2019). "Although much of the early work on this response centered on the contribution of Th2 cells, we now understand that ILC2s are an important contributor of IL-13 produced early on during infection." (PMID 31019505, 2019). "ILC2s isolated from IL-33-treated mice had 2.5-fold increase in IL-13+ ILC2s during infection compared with controls." (PMID 31221971, 2019). "Specifically, IL-5 and IL-13, which have been shown to activate the defense response to C. neoformans infection, were significantly induced in the mouse infection assay." (PMID 31329596, 2019). "Concentrations of inflammatory and immunomodulatory cytokines IL-1β, IL-6, TNF-α, IL-10, and IL-13 were significantly greater in BAL samples of Nrf2 KO mice compared to WT controls at day 1 after infection (p < 0.05)." (PMID 29740449, 2018). "In line with the clinical findings, C57BL/6 IFN-β−/−, IFNAR1−/−, and WT mice exhibited similar mRNA expression levels of IFN-γ, interleukin (IL)-4, IL-12, IL-13, inducible nitric oxide synthase, and arginase 1 during the acute and late phase of the infection." (PMID 29459858, 2018). "IgG1 and IL-13, typical markers of the TH2 response associated with effective worm clearance, were significantly higher following a ZT0 infection." (PMID 29491349, 2018).
infection (continued). "At day 6 post-infection the increase in Il5 and Il13 mRNA expression in total lung was significantly reduced following anti-Ym1 treatment whilst Il4 was not significantly altered." (PMID 30500858, 2018). "To address this, we first analyzed the number of hepatic ILC2s and production of IL-13 by hepatic ILC2s during infection using flow cytometry." (PMID 29554131, 2018). "It is worth mentioning here that the mammalian key type 2 cytokine, IL-4, has been shown in the avian immune system to be less expressed compared to IL-13 in several extracellular infection models, hence measuring IL-13 was opted in the current study." (PMID 29892298, 2018). "It has been reported that inflammatory cytokines, including TNF-α, IL-4, and IL-13, promote mucin gene expression in intestinal epithelial cells and prevent pathogen infection and colonization." (PMID 29867964, 2018). "Studies on experimental and natural human infections with hookworms have observed that the infection triggers strong Th2 cytokines (especially IL-4, IL-5, IL-9 and IL-13), regulatory IL-10 and TGF-β1 responses." (PMID 30274434, 2018). "In adult mice as well, ILC2 are elicited upon RSV infection (strain 01/2-20, human isolate, propagated in Hep-2 cells) and the main source of IL-13 early in the infection leading to AHR, goblet cell hyperplasia, and increased mucus production." (PMID 29760695, 2018). "Analyzing mRNA for components of L-arginine metabolism, we observed that the effect of IL-4 on infection progression was via the increase of Arg1 and Larg mRNAs, while the effect of IL-13 on infection progression was only via the increase in Larg mRNA." (PMID 30150896, 2018). "Analysis of the lungs 35 days after infection showed that a majority of cells producing IL-13 were NKT cells, while CD4 T cells predominantly expressed IFNγ." (PMID 29915592, 2018). "Increased differentiation of Th1 and Th17 cells after fbp1Δ mutant yeast infection was accompanied by decreased differentiation of IL-4 -, IL-5 -, and IL-13 -producing Th2 cells compared to H99 infection." (PMID 29317510, 2018). "The major cellular source of IL-13 changes from the CD4+ T cell at day 21 after infection to macrophages at 7 weeks after infection." (PMID 30513770, 2018). "IL-13 and IL-9 cytokine production by infection-primed lymphocytes was highest in response to stimulation with sub-groups 3 and 4, whereas the highest anti-parasite antibody levels were measured in response to sub-group 2." (PMID 29540816, 2018). "We present evidences in favor of a key role for macrophave-derived Chi3l3 molecule in the infection of Angiostrongylus cantonensis, which aggravates eosinophilic meningitis induced by Angiostrongylus cantonensis via a IL-13-mediated positive feedback loop." (PMID 29391024, 2018). "Accordingly, pre-infection with S. venezuelensis also enhanced the expression of mRNA for IL-5 and IL-13 in the lungs." (PMID 30283458, 2018). "Our data indicated that ILC2s were a primary source of IL-13 production in the infected livers, and both the number of ILC2s and production of IL-13 in these cells were increased by day 32 post-infection, peaking at day 42 post-infection." (PMID 29554131, 2018). "Our data showed that the initial elevation of IL-13 in hepatic ILC2 cells (day 32 post-infection) occurs prior to the elevation of IL-33 in whole livers and HSCs (day 42 post-infection)." (PMID 29554131, 2018). "The absence of any distinct separation in the relative levels of IFN-γ and IL-13 mRNA expressing cells in turkeys suggests that both type 1 and type 2 immune responses have been elicited during vaccination or infection." (PMID 29892298, 2018). "Together, during infection with T. cruzi IL-13 induces an increased arginase activity and subsequently elevated amounts of polyamines." (PMID 30555475, 2018).
infection (continued). "We present evidences in favor of a key role for macrophage-derived Chi3l3 molecule in the infection of Angiostrongylus cantonensis, which aggravates eosinophilic meningitis induced by Angiostrongylus cantonensis via a IL-13-mediated positive feedback loop." (PMID 29391024, 2018). "Murine infection with the lung migrating nematode, Nippostrongylus brasiliensis, elicits a strongly polarised type 2 response, characterised by IL-4, IL-13, IL-5 and IL-9 cytokines." (PMID 30500858, 2018). "We show that miR-203-3p targets interleukin-33 (IL-33), an inducer of type 2 immunity, in hepatic stellate cells to regulate the expansion and IL-13 production of hepatic group 2 innate lymphoid cells during infection." (PMID 29554131, 2018). "The titers of IL-13 were also detectable early in infection and peaked at 20.11 pg/mL at 2 dpi, before gradually decreasing." (PMID 29511145, 2018). "The PM exposure further upregulated the expression of IL-8 but downregulated the expression of IL-13 upon infection." (PMID 29310642, 2018). "In our study, we only found significant difference of TNF-α response in the 2000 CFU level of infection between the two strains, same as other cytokines including IL-4, IL-10, GM-CSF, IL-1β, IL-2, IL-6, IL-13, and IL-18." (PMID 30577452, 2018). "infection induced Th2-biased immune responses with elevated synthesis of IgE and IgG1 and an increased splenocyte production of IL-5, IL-10 and IL-13." (PMID 28606183, 2017). "In order to determine the cellular source of IL-13 at the site of infection, we injected brefeldin A into mice infected with H. polygyrus, at day 7 post infection." (PMID 29045902, 2017). "Production of Th2 cytokines (IL-4, IL-5, IL-10 and IL-13) by MLN cells similarly peaked at day 6–7 post infection and gradually declined thereafter." (PMID 28651009, 2017). "Samples from two independent experiments revealed a significant, infection time-dependent suppression of IL-13, a classical type 2 cytokine, especially at the late stages (day 10) of infection." (PMID 28742087, 2017). "In contrast to the site of infection, Il13 mRNA expression within the draining mLN was similar in both mouse strains." (PMID 29045902, 2017). "Re-challenging these chronically infected mice with a high dose infection resulted in the induction of Muc2 and Il13 expression and a reduction in Ifnγ expression." (PMID 28192541, 2017). "Together, these results support the notion that pulmonary IL-13 shapes the immune environment in the lung, which upon infection delays the induction of innate defenses against pathogens." (PMID 28228256, 2017). "Supplementation of IL-13 at this stage of infection resulted in significantly lower egg counts and worm burdens in infected Egfrfl/flxCd4-cre mice, fully reverting their susceptible phenotype." (PMID 29045902, 2017). "The induction of a prevalent Th2-type response, with the production of IL-4, IL-5, and IL-13, results in a less robust and less efficient reaction to the infection, clinically presenting as increased disease severity and risk for future recurrent wheezing." (PMID 29206851, 2017). "Levels of IL-5 and IL-13 in nasal lining fluid tend to be high before infection (day 0) in those individuals that developed the highest levels after rhinovirus infection." (PMID 28373098, 2017). "The magnitude of the IFN-γ response to infection is relatively large compared to type 2 cytokine induction, but induction of IL-5 and IL-13 is more selective for allergic asthmatics compared to controls." (PMID 28373098, 2017). "TH1-cytokines (TNF-α, IFN-γ, IL-12p70) and TH2-cytokines (IL-4, IL-10, IL-13) were measured 8 weeks after initial infection." (PMID 28542175, 2017). "The IL-4, IL-6, IL-10, IL-13 levels of Th2 cells continued to increase after infection during the first 9 weeks post-infection and down-regulated thereafter." (PMID 29192177, 2017).